CYP19A1 (cytochrome P450 family 19 subfamily A member 1)
Diseases named in the same sentence as CYP19A1 in open-access papers (continued):
Sharing a sentence is not in itself a finding about the gene and the disease.
gastric cancer (12 papers, 2012 to 2025). A primary or metastatic malignant neoplasm involving the stomach. "For instance, CYP19A1, a steroid synthetase, has been implicated in promoting the progression of gastric cancer." (PMID 38102546, 2023). "Our finding of a suggestive association between the CYP19A1 gene variant and stomach cancer contrasts with observational studies which have shown that menopausal hormone therapy is associated with a lower risk of stomach cancer." (PMID 34601599, 2022). "Both the genetic variants rs12190287 of TCF21 and rs10046 of CYP19A1 have been studied in multiple cancers which include breast, lung, neck, and gastric cancer." (PMID 32487238, 2020). "Pooled- and meta-analyses showed CYP19A1 was statistically significantly associated with gastric cancer risk." (PMID 23110082, 2012). "A Japanese study observed a statistically significant association between several CYP19A1 SNPs (rs4646 and rs1902586) and gastric cancer risk." (PMID 23110082, 2012). "Pooled- and meta-analyses showed CYP19A1 rs1004982, rs16964228, and rs1902580 had an increased risk for gastric cancer (pooled OR [95% CI] = 1.22 [1.01–1.48], 1.31 [1.03–1.66], 3.03 [1.12–8.18], respectively)." (PMID 23110082, 2012). "CYP19A1 genetic polymorphisms, specifically rs1004982, rs16964228, rs1902580, were associated with an increased risk for gastric cancer in the current study." (PMID 23110082, 2012). "In summary, this population-based two-phase genetic association study reports CYP19A1 genetic variants, rs16964228, rs1902580, and rs1004982, are significantly associated with gastric cancer risk and appear to be a genetic marker of susceptibility in gastric carcinogenesis in the Korean population." (PMID 23110082, 2012). "Our findings suggest CYP19A1 that codes aromatase may play an important role in the association of gastric cancer risk and be a genetic marker for gastric cancer susceptibility." (PMID 23110082, 2012). "Our findings suggest the possibility that genetic variants of CYP19A1 (rs1004982, rs16964228, and rs1902580) might be involved in altering estrogen levels and affecting apoptosis, mucosal function, carcinogenesis, and thus gastric cancer risk." (PMID 23110082, 2012). "A preceding study demonstrated that approximately 20% of patients diagnosed with gastric cancer exhibited an excess of the CYP19A1 gene." (PMID 41415563, 2025). "Silencing of the CYP19A1 gene has been demonstrated to exert a growth-inhibiting effect on gastric cancer cells." (PMID 41415563, 2025). "It is reported that CYP19A1 was a potential biomarker for gastric cancer prognosis and immune cell infiltration." (PMID 39206151, 2024). "A series of basic laboratory experiments also verified the functional role of CYP19A1 in gastric cancer." (PMID 37784135, 2023). "Last but not least, only the role CYP19A1 plays in gastric cancer was explored and the molecular mechanisms underlying this phenomenon remain studied." (PMID 37784135, 2023). "Above all, quantitative real-time PCR (qRT-RCR) was used to validate the expression level of CYP19A1 in several common gastric cancer cell lines and the results showed that some of the gastric cancer cell lines exhibited high CYP19A1 expression with statistical significance." (PMID 37784135, 2023). "CYP19A1/aromatase (Ar) is a prognostic biomarker of gastric cancer (GCa)." (PMID 31557413, 2019). "The objective of the study was to investigate the role of genes (HSD3B1, CYP17A1, CYP19A1, HSD17B2, HSD17B1) involved in the steroid hormone biosynthesis pathway and progesterone receptor (PGR) in the etiology of gastric cancer in a population-based two-phase genetic association study." (PMID 23110082, 2012). "These key genes (UGT1A1, ADH4, ADH1B, CYP19A1, and GPX3) are crucial for the construction of our gastric cancer (GC) prognostic model." (PMID 41031088, 2025).
gastric cancer (continued). "Although the functional relevance of CYP19A1 rs16964228, rs1902580, and rs1004982 for CYP19 enzyme is not clear, CYP19A1 may act as a key marker of individual susceptibility and its genetic variants can modify the development of gastric cancer, but further confirmation is warranted." (PMID 23110082, 2012).
colorectal cancer (11 papers, 2007 to 2025). A primary or metastatic malignant neoplasm that affects the colon or rectum. "In the present study, a haplotype block (block #5 in our analysis) in CYP19A1 was associated with colorectal cancer, with 2 haplotypes reaching pointwise significance levels." (PMID 21627810, 2011). "Our findings offer some support for a suggestive association of CYP17A1 and CYP19A1 variants with colorectal cancer risk." (PMID 21627810, 2011). "The 5th block of the CYP19A1 gene, which contains the promoter region with 8 tagging SNPs including rs1902584, was significantly associated with colorectal cancer risk (corrected global p value = 0.02)." (PMID 21627810, 2011). "Our findings in women who later developed colorectal cancer also suggest that the observed association between CYP19A1 and HGF levels may be more relevant to cancer population." (PMID 22848710, 2012). "In addition, an LD block in CYP19A1 which includes the promoter region was significantly associated with risk for colorectal cancer." (PMID 21627810, 2011). "Moreover, one haplotype block of CYP19A1 was associated with colorectal cancer (corrected global p value = 0.02), which likely reflected the association with the tagging SNP, rs1902584, in the block." (PMID 21627810, 2011). "In that study the authors report three SNPs, rs10046 in CYP19A1, rs2911422 and rs2042429 in HSD17B2 genes, that were marginally associated with colorectal cancer risk." (PMID 36302831, 2022). "We evaluated 45 common and putative functional variants of CYP19A1 and circulating levels of HGF among 260 postmenopausal women who later developed colorectal cancer from the Women's Health Initiative Observational Cohort." (PMID 22848710, 2012). "Moreover, by targeting the inhibition of CYP19A1, Anastrozole also effectively reversed the chemoresistance of colorectal cancer cells." (PMID 41050076, 2025). "Thus, the findings may not be applicable to the general population, although both CYP19A1 variants and HGF levels were not strongly associated with colorectal cancer risk." (PMID 22848710, 2012).
osteoporosis (9 papers, 2007 to 2026). A condition of reduced bone mass, with decreased cortical thickness and a decrease in the number and size of the trabeculae of cancellous bone (but normal chemical composition), resulting in increased fracture incidence. "CYP19A1, an aromatase-encoding gene, is known to be related to osteoporosis and can influence BMD by altering the levels of estrogen." (PMID 33178024, 2020). "Several polymorphisms in the aromatase or CYP19A1 have been reported to be associated with hormone-related disease such as osteoporosis and breast cancer." (PMID 27994616, 2016). "It seems that the CYP19A1 rs700518 polymorphism may be a potential marker used in the early prevention, diagnosis, and therapy of osteoporosis." (PMID 35743606, 2022). "Additionally, it was worth observing that the CYP19A1 gene demonstrates its role by being associated with the osteoporosis." (PMID 29312992, 2017). "The CYP19A1 polymorphism is related to bone mineral density (BMD), and rs700518 is one of the most studied polymorphisms in association with BMD and osteoporosis." (PMID 35743606, 2022). "The CYP19A1 rs700518 polymorphism is based on the conversion of adenine (A) to guanine (G) and is one of the most widely studied polymorphisms in relation to bone mineral density (BMD) and osteoporosis." (PMID 35743606, 2022). "Many authors have observed that CYP19A1 gene mutations are associated with BMD and their presence may contribute to the development of osteoporosis." (PMID 35743606, 2022). "SNPs in, for example, the drug metabolic enzyme cytochrome P450 19A1 (CYP19A1) and the estrogen receptor 1 (ERS1) gene have been related to the risk for AI-related side effects, but mainly in relation to the development of arthralgias, menopausal symptoms, and osteoporosis." (PMID 36230587, 2022). "The serum levels of VDR and CYP19A1 were reduced following the administration of TBD, suggesting that TBD is able to treat OVX-induced osteoporosis by ameliorating the levels of VDR and CYP19A1." (PMID 33178024, 2020).
prostate carcinoma (9 papers, 2011 to 2023). A carcinoma that arises from epithelial cells of the prostate gland. "CYP19A1 is also expressed in prostate cancer where it is associated with longer time to disease progression." (PMID 37188267, 2023). "The promoter gene polymorphism of CYP19A1 has been linked with the risk of hepatocellular carcinoma; in addition, it can promote the metastatic homing and proliferation of stem-like prostate cancer cells in the bone marrow." (PMID 34147074, 2021). "HeyL overexpression increased endogenous estradiol levels and estrogen receptor-α (ERα) transcriptional activity by upregulating CYP19A1 expression, which encodes aromatase, enhancing prostate cancer stem cell (PCSC) properties in PC3 cells." (PMID 35096586, 2021).
autism (8 papers, 2013 to 2022). Persistent deficits in social interaction and communication and interaction as well as a markedly restricted repertoire of activity and interest as well as repetitive patterns of behavior. "CYP19A1 has also been associated with autism by genetic studies." (PMID 23697635, 2013). "Evidence pointing toward the importance of such enzymes was previously found via genetic associations between autism and single-nucleotide polymorphisms in CYP17A1, CYP19A1, and CYP11B1 genes." (PMID 31075898, 2019). "Prior evidence pointing toward the importance of such enzymes was previously found via genetic associations between autism and single-nucleotide polymorphisms in CYP17A1, CYP19A1 and CYP11B1 genes." (PMID 24888361, 2015). "Interestingly, in a genetic association study, Chakrabarti and colleagues identified variations in the ARNT2 gene, ESR1, ESR2 and also CYP19A1 to be associated with ASC diagnosis and/or autism traits in the general population." (PMID 26066795, 2015). "A genetic study of autism found evidence that single nucleotide polymorphisms in sex steroid synthesis genes (ESR2, CYP11B1, CYP17A1, CYP19A1) were associated with autism traits and autism without intellectual disability and good verbal skills." (PMID 30570672, 2019).
dyslexia (8 papers, 2012 to 2025). A learning disorder characterized by an impairment in processing written words. "Variations in CYP19A1 are also associated with dyslexia as a categorical trait and quantitative disruptions in reading, vocabulary, phonological processing, and oral motor skills." (PMID 30386297, 2018). "Our results suggest that variations in CYP19A1 are associated with dyslexia as a categorical trait and with quantitative measures of language and speech, such as reading, vocabulary, phonological processing and oral motor skills." (PMID 22426781, 2012). "In summary, three of the four cohorts where family material was available, do show a moderate (p-values significant at the 0.05 level) association between dyslexia, as a categorical trait, and a number of SNP/haplotypes from the CYP19A1 gene." (PMID 22426781, 2012). "Expression of CYP19A1 correlates with expression of dyslexia-risk genes DYX1C1 and ROBO1 raising questions as to whether CYP19A1 acts independently on dyslexia risk." (PMID 36452335, 2022). "Two proposed candidate genes located on chromosome 15q21 that may bring clues to an environmental link to the susceptibility of dyslexia are CYP19A1 and DYX1C1." (PMID 28241485, 2017). "Of note, the genomic region 15q in which DYX1C1 and CYP19A1 are located also contains several susceptibility genes for ADHD, a comorbidity of dyslexia." (PMID 28241485, 2017). "As the promoter analysis suggested similar transcription factor binding sites for CYP19A1 and the dyslexia susceptibility gene DYX1C1, we studied the expression levels of CYP19A1 and the six dyslexia-associated genes reported so far." (PMID 22426781, 2012). "Some evidence for association of SNP haplotypes in CYP19A1 with dyslexia defined categorically was found in Finnish and US dyslexia cohorts, but not in a German one." (PMID 23308072, 2012). "Targeted sequencing of two genes in the dyslexia-risk locus DYX1 on chromosome 15 provides no support for a role for DNAAF4 in modulating performance on any tested trait but does implicate a common variant downstream of CYP19A1." (PMID 40424442, 2025). "We present additional evidence for a role in dyslexia risk for DCDC2, KIAA0319, GRIN2B and CYP19A1, but not for DNAAF4." (PMID 40424442, 2025).
colon cancer (7 papers, 2021 to 2025). "CYP19A1 gene expression was a strong prognostic risk factor in the colon cancer, and positively correlated with PD-L1 expression in the GEPIA webserver." (PMID 37055842, 2023). "In addition, it has been observed in clinical samples that single nucleotide polymorphism mutations in CYP19A1 are independently associated with colon cancer." (PMID 38045683, 2023). "In the context of colon cancer immunotherapy, the inhibition of CYP19A1 combined with PD-1 blockade was proposed as a promising therapeutic strategy." (PMID 39457539, 2024). "CYP19A1 has been identified as a key player in lipid metabolism and immune microenvironment modulation in colon cancer, with targeting strategies showing promise for enhancing immunotherapy efficacy and serving as a prognostic predictor." (PMID 39204124, 2024). "Together, our results demonstrate that CYP19A1 inhibition drastically enhances anti-PD-1 therapy for colon cancer." (PMID 37055842, 2023). "The hub genes including CYP19A1 were identified by the protein–protein interaction network of differentially expressed LMGs in the colon cancer." (PMID 37055842, 2023). "Our extensive functional studies demonstrated that CYP19A1 protein expression was positively correlated with PD-L1 expression and infiltration of macrophages, CAFs and endothelial cells in human colon cancer tissues." (PMID 37055842, 2023). "Among the differentially expressed lipid metabolism genes in colon cancer and adjacent normal tissues, CYP19A1 is a key molecular node and has the largest prognostic hazard ratio." (PMID 37055842, 2023). "Next, we verified the factors derived from tumor cells in HT29 and HCT116 colon cancer cells, and comfirmed that CYP19A1 inhibition significantly reduced PD-L1, IL-6, and TGF-β expression in tumor cells." (PMID 37055842, 2023). "CYP19A1 inhibition combined with PD-1 blockade represents a promising therapeutic strategy for colon cancer immunotherapy." (PMID 37055842, 2023). "Next, mIF staining was performed to explore the relationship between CYP19A1 expression and immune landscape in the colon cancer." (PMID 37055842, 2023). "Overall, these findings strongly indicate that CYP19A1 inhibition greatly facilitates anti-PD-1 therapy for colon cancer." (PMID 37055842, 2023). "Given that strong correlations of the LMrisk with PD-L1 expression, TMB and MSI, we conclude that the LMrisk including CYP19A1 is a promising biomarker for predicting immunotherapeutic response to colon cancer." (PMID 37055842, 2023). "The infiltration of CD8+ T cells was more but the proportions of CD68+ cells (macrophages), α-SMA+ cells (CAFs) and CD31+ cells (endothelial cells) were fewer in human colon cancer tissues with low CYP19A1 expression as compared with high CYP19A1 expression." (PMID 37055842, 2023). "We found that CYP19A1 gene was highly expressed in the colon cancer tissues compared to the adjacent normal tissues in the Gene Expression Profiling Interactive Analysis (GEPIA) webserver." (PMID 37055842, 2023). "CYP19A1 protein expression was an independent prognostic factor, and positively correlated with PD-L1 expression in human colon cancer tissues." (PMID 37055842, 2023). "Similarly, CYP19A1 protein expression was significantly increased in human colon cancer tissues, and positively correlated with PD-L1 expression." (PMID 37055842, 2023). "Our study develops a novel lipid metabolism-related risk model to predict immunotherapeutic response, and elucidates the molecular mechanism by which CYP19A1-catalyzed estrogen synthesis mediates immune escape, providing new targets and candidates for sensitizing colon cancer immunotherapy." (PMID 37055842, 2023). "Importantly, CYP19A1 inhibition improves anti-PD-1 immunotherapy for colon cancer and blunts PD-L1-induced anergy of CD8+ T cells." (PMID 37055842, 2023).